GYS1 (glycogen synthase 1)
Diseases named in the same sentence as GYS1 in open-access papers (continued):
Sharing a sentence is not in itself a finding about the gene and the disease.
tumor (21 papers, 2011 to 2025). "By conducting an analysis of the tumor microenvironment, it was determined that the high-risk score group, which included GYS1, displayed a notable increase in both Stromal score and Immune score." (PMID 39308675, 2024). "Based on the association of tumor GYS1 mRNA expression with overall survival in patients with TNBC specifically and their high GYS1 protein expression, we selected three TNBC cell lines (HCC1806, MDA-MB-231, SUM159PT) and one ER + cell line (MCF7) for further analyses." (PMID 37280675, 2023). "It has been reported that GYS1 triggers glycogen accumulation and leads to tumor progression through activating NF-κB signaling." (PMID 39605832, 2024). "Among the disulfidptosis genes, the role of GYS1 in tumor progression was further experimentally verified." (PMID 39605832, 2024). "We found that the GYS1 knockdown group exhibited a statistically significant reduction in both tumor weight and volume compared with the control group." (PMID 38420162, 2024). "Among the disulfidptosis genes, it was experimentally evidenced that suppression of GYS1 effectively hindered tumor cell growth." (PMID 39605832, 2024). "To evaluate tumor growth upon long-term vs. acute GYS1-knockdown and in an in vivo setting, we constructed a short-hairpin GYS1-knockdown MDA-MB-231 cell line." (PMID 37280675, 2023). "Cytoplasmic GYS1 staining was present in all shCtrl xenografts, with higher intensity in areas adjacent to the necrotic tumor core compared to the outer tumor border." (PMID 37280675, 2023). "Our in vivo data suggest a similar effect of hypoxia, since GYS1 protein expression in control xenografts was highest adjacent to the necrotic tumor core." (PMID 37280675, 2023). "Taken together, our results showed that deletion of Drp1 in APC-derived tumor organoids promotes the expression of GYS1 and glycogen accumulation." (PMID 37816729, 2023). "At the protein level, GYS1 expression was relatively higher in 11 of 12 ccRCC than in matched non-tumor tissues." (PMID 32802186, 2020). "Overexpression of GYS1 promoted tumor growth whereas its silencing suppressed it by activating the canonical NF-κB pathway." (PMID 32802186, 2020). "We found that GYS1 mRNA expression was significantly increased in tumor tissues compared to in normal tissues in the Jones Renal dataset." (PMID 32802186, 2020). "It is notable that mRNA levels of glycogen biosynthetic enzymes GYS1/2 and GBE1 were associated with poor survival in AML and that invalidation of GYS1 delayed tumor growth in vivo." (PMID 31319822, 2019). "Therefore, in vivo experiments such as patient‐derived tumor xenograft models need to be conducted, and the combination of GYS1 inhibitors with classic anti‐tumor drugs is imperative to be explored in forthcoming studies." (PMID 38420162, 2024). "GYS1 affects immune cell, especially M2 macrophage infiltration in the tumor microenvironment." (PMID 38223725, 2024). "Furthermore, we demonstrated that silencing GYS1 effectively inhibits the tumor proliferation and metastasis of HBV-HCC in vitro and in vivo." (PMID 39308675, 2024). "Specificly, NCKAP1 may affect prognosis by influencing tumor proliferation, invasion, and migration, while GYS1 may affect prognosis by influencing the immunosuppressive microenvironment." (PMID 38223725, 2024). "Knockdown of disulfidptosis gene GYS1 effectively hindered tumor progression." (PMID 39605832, 2024). "Additionally, we assessed GYS1 mRNA levels using RT-qPCR and verified that GYS1 gene expression was upregulated in Apc/Drp1-KO compared to Apc tumor organoids." (PMID 37816729, 2023). "Mechanistically, increased AMPK activation promotes GYS1 expression to facilitate glycogen synthesis in multiple model systems, including Drp1 knockdown colon cell lines, Drp1 knockout Apc-driven tumor organoids and xenograft tumor tissues derived from Drp1 knockdown cells." (PMID 37816729, 2023).
tumor (continued). "Next, to test whether glycogen metabolism is required for tumor growth in vivo, A673 WT and GYS1‐KO cells were injected subcutaneously into athymic nude mice." (PMID 36059248, 2022). "Additionally, significant increase of expression in tumor tissues, high expression of GYS1, HK2 and SLC2A were significantly correlated with decreased survival of LIHC patients in the TCGA cohort." (PMID 34059694, 2021). "Previous studies have demonstrated that GYS1 is involved in tumor cell proliferation." (PMID 30100905, 2018). "Because the AMPK pathway has also been reported to be involved in glycogenesis by regulating GYS1 phosphorylation and GYS1 expression in tumor cells, we evaluated whether AMPK also modulates GYS1-mediated glycogenesis in RA FLSs." (PMID 30100905, 2018). "Additionally, numerous studies have shown that GYS1 participates in tumor growth and progression through different mechanisms such as via the nuclear factor kappa‐B (NF‐κB) pathway, the AMP‐activated protein kinase (AMPK) pathway, and the hypoxic inducible factor‐1 alpha (HIF‐1α) pathway." (PMID 38420162, 2024). "Furthermore, we tested whether the GYS1 small molecule inhibitor guaiacol (GYSi) could delay tumor growth in vivo." (PMID 36059248, 2022). "Thus, we hypothesized that GYS1 might promote cellular glycogen synthesis and accumulation, which provides the raw material for tumor cells to maintain a high level of the NADPH pool, thus providing critical reducing capacity to counteract disulfide stress and maintain cell survival." (PMID 38420162, 2024). "Aberrant DNA methylation of the disulfidptosis genes was also investigated in cancers, such as hypermethylation of GYS1 in CHOL, and hypomethylation of SLC7A11 in most tumor types." (PMID 39605832, 2024). "Ultimately, we assessed the impact of GYS1, a prognostic molecule, on the growth and metastasis of HBV-HCC tumor both in vitro and in vivo." (PMID 39308675, 2024). "The results showed that HK2, PGM1, PPP1R3C, GYS1, and G6PD were significantly up-regulated in ccRCC tumor tissues." (PMID 34522206, 2021). "The aim of this study was to identify the clinical significance, biological function, and molecular regulation of glycogen synthase 1 (GYS1) in ccRCC glycogen accumulation and tumor progression." (PMID 32802186, 2020). "In this single xenograft #7, half of the tumor showed re-expression of GYS1 mRNA and protein whereas the other half was negative for GYS1." (PMID 37280675, 2023). "Tumor tissues with high c-Met expression level in TCGA have increased expression of H6PD, PDK2, PDK4, PDPR, PKLR, SLC2A2 genes whereas decreased expression of GYS1, HK1, HK2, SLC2A1, significantly." (PMID 34059694, 2021). "Statistical analysis revealed relatively higher IHC score of GYS1 in tumor samples than in paired non-tumor samples." (PMID 32802186, 2020). "While GYS1‐KO did not affect cell viability in vitro, we postulate that this is due to the artificial environment of cell culture (21% O2, 25 mM glucose) with in vitro conditions not replicating the ES tumor microenvironment in vivo." (PMID 36059248, 2022). "The expression of GYS1 is HIF1α-dependent, but PYGL is not consistently HIF1α-dependent; PYGL depletion impairs tumor growth, as glycogen breakdown is integral to tumor cell function and growth." (PMID 38028629, 2023).
cancer (17 papers, 2010 to 2025). A tumor composed of atypical neoplastic, often pleomorphic cells that invade other tissues. "The disulfidptosis genes: NCKAP1, LRPPRC, SLC7A11, OXSM, SLC3A2, NDUFS1, and GYS1 occurred somatic mutations in pan-cancer, with 1 % SNV frequency." (PMID 39605832, 2024). "Amplifications in genes such as SLC3A2, OXSM, and GYS1 were linked to increased expression in cancer tissues, whereas genes such as NDUFS1 and NCKAP1 showed reduced expression, underscoring the diverse impact of DRG expression on BLCA pathology." (PMID 38507521, 2024). "However, we still lack sufficient evidence whether GYS1 serves as a key potential hallmark of cancer." (PMID 32802186, 2020). "GYS1 expression was remarkably suppressed through transiently transfecting si-GYS1 in three cancer cell lines: ACHN, CAL-27, and NCI-H23." (PMID 39605832, 2024). "Data from cancer genomics has indicated a correlation between heightened levels of glycogen synthase 1 and 2 (GYS1/2) or glycogen branching enzyme 1 with unfavorable outcomes in AML patients." (PMID 39312378, 2024). "The results revealed that SLC7A11, SLC3A2, RPN1, LRPPRC, and GYS1 were highly expressed in several cancer tissues." (PMID 38271056, 2024). "Other top biomarkers predicted response to histone deacetylate inhibitor JNJ-26481585, including GYS1, involved in glycogen metabolism, known to be reprogrammed in cancer cells." (PMID 33690666, 2021). "Four of these genes, AKT2, AKT3, G6PC, and GYS1, were particularly interesting because their involvement in the regulation of glycolysis in cancer has been well documented." (PMID 26512921, 2015). "It was thus evidenced that GYS1 was a possible treatment target of human cancers." (PMID 39605832, 2024). "In addition, proliferative capacities of the three cancer cells were prominently attenuated in the context of GYS1 suppression." (PMID 39605832, 2024). "We further explored the function role of GYS1 in the Pan-cancers." (PMID 39605832, 2024). "Hypoxia-inducible factor-1α can induce glycogen synthesis and GYS1 expression in cancer cells." (PMID 30100905, 2018). "Further work is required to test this hypothesis and to investigate the potential role of GYS1 as a target for therapeutic intervention in cancer." (PMID 20300197, 2010). "We found that the expression of GYS1 and SLC7A11 were upregulated, while those of NCKAP1, NDUFS1, NUBPL, OXSM, RPN1, and SLC3A2 were downregulated in ccRCC tissues compared with those in the para-carcinoma tissues." (PMID 38271056, 2024). "This is in line with a previous study reporting that stable GYS1 knock-out did not impair the growth of glycogen positive renal clear cell (RCC) cancer cells." (PMID 37280675, 2023). "Glycogen accumulation and increased GYS1 expression under a hypoxic microenvironment have also been observed in some cancer and noncancer cell lines; however, it is unclear if inflammatory conditions affect cellular glycogen synthesis." (PMID 30100905, 2018).
myopathy (5 papers, 2010 to 2025). A disease of the muscle in which the muscle fibers do not function properly. "Type 1 polysaccharide storage myopathy caused by genetic mutation in the glycogen synthase 1 gene is present in many breeds including the Noriker and Haflinger horses." (PMID 33609063, 2021). "Finally, because the genetic basis of type 1 polysaccharide storage myopathy has recently been identified, we aimed to test a group of susceptible Standardbred horses for the presence of the associated GYS1 mutation." (PMID 20644724, 2010). "To assess if therapeutic treatment with Gys1 ASO could reverse the glycogen accumulation and myopathy in aged model, we dosed Gaa−/− mice with Gys1 ASO#2 starting at 3 months of age (Cohort 2)." (PMID 40268518, 2025). "Thirty‐two horses (11 Haflinger and 21 Noriker horses) with homozygous non‐affected (GG), heterozygous affected (GA) and homozygous affected (AA) status of GYS1 mutation without overt clinical signs of any myopathy were selected for the current study." (PMID 33609063, 2021).
infection (2 papers, 2016 to 2018). The state of being infected such as from the introduction of a foreign agent such as serum, vaccine, antigenic substance or organism. "When we deprived the cells of Glc for two days before infection, and thus decreased cytoplasmic glycogen, Gys1 staining in the inclusion lumen was considerably reduced, while remaining abundant in the cytoplasm." (PMID 26981769, 2016). "Staining was specific since it disappeared when Gys1 expression was knocked down using siRNA prior to infection." (PMID 26981769, 2016). "Cells were transfected with siRNA against Gys1 two days before infection." (PMID 26981769, 2016). "We depleted Gys1 and SLC35D2 for 48 hr before infecting the cells, and applied PAS staining 48 hr after infection." (PMID 26981769, 2016).
cardiac diseases (1 paper, 2024). "GYS1, which was increased in HCM patients by our findings, has been reported to be related to heart metabolism and cardiac diseases." (PMID 39701955, 2024).
inflammation (1 paper, 2018). Aberrant reaction of the microcirculation characterized by movement of fluid and leukocytes from the blood into extravascular tissues. "In summary, our findings demonstrate that GYS1-mediated glycogen accumulation plays an important role in regulating rheumatoid synovial inflammation by blocking excessive AMPK activation, providing a novel approach to understanding the mechanisms of RA." (PMID 30100905, 2018). "A model for the role of GYS1 in regulation of rheumatoid synovial inflammation and joint destruction is proposed in." (PMID 30100905, 2018).
GYS1 also shares sentences with these, for which no sentence is quoted: hyperlipidemia (2 papers); myelodysplastic syndrome (2); Obesity (2); triple-negative breast carcinoma (2); astrocytoma (1); atherosclerosis (1); cardiovascular disease (1); Cirrhosis (1); depression (1); ductal carcinoma in situ (1); Glucose intolerance (1); glycogen storage disease (1); hyperglycaemia (1); Hyperinsulinemia (1); intrauterine growth restriction (1); liposarcoma (1); liver fibrosis (1); metabolic disease (1); neurodegenerative disease (1); non-small cell lung carcinoma (1); Rectal prolapse (1); rheumatoid arthritis (1); schizophrenia (1).